CDC73 (cell division cycle 73)
Diseases named in the same sentence as CDC73 in open-access papers (continued):
Sharing a sentence is not in itself a finding about the gene and the disease.
glioblastoma (1 paper, 2025). The most malignant astrocytic tumor (WHO grade IV). "Among which, CDC73, PSMC2, SOCS3, and ETV4 were substantially upregulated; whereas PLK2 and LMO7 were substantially downregulated in glioblastoma cells than that in control." (PMID 41318472, 2025).
hyperlipidemia (1 paper, 2011). "We identified seven CNV regions that were associated significantly with hyperlipidemia and myocardial infarction in our patients through multistage analysis (P<0.001), at 1p21.3, 1q31.2 (CDC73), 1q42.2 (DISC1), 3p21.31 (CDCP1), 10q11.21 (RET) 12p12.3 (PIK3C2G) and 16q23.3 (CDH13), respectively." (PMID 22369086, 2011).
jaw neoplasm (1 paper, 2024). "We used search keywords (in different combinations) such as “hyperparathyroidism jaw tumour syndrome” (alternatively, “hyperparathyroidism” or “parathyroid”) and “jaw neoplasm”, “jaw syndrome”, “parafibromin”, or “CDC73”." (PMID 38396977, 2024).
lobular carcinoma (1 paper, 2017). "A higher CDC73 expression was seen in breast ductal and/or lobular carcinoma than normal tissue (p<0.05)." (PMID 29221126, 2017).
mesenchymal tumors (1 paper, 2024).
myeloma (1 paper, 2025). "To investigate the presence of the endogenous SEI1/CBP/p300/PAF1 complex in myeloma cells, we performed immunoprecipitation assays using anti‐SEI1, PAF1, CDC73, or p300 antibodies on myeloma cell lysates." (PMID 40135791, 2025). "Our results confirmed the presence of PAF1, CDC73, or p300 in the immunoprecipitates, indicating the existence of the SEI1/CBP/p300/PAF1 complex in myeloma cells." (PMID 40135791, 2025).
oral cancer (1 paper, 2019). "For example, miR-155 is up-regulated in oral cancer and its dys-regulation is associated with the low level of cell division cycle 73 (CDC73), a tumor suppressor gene; therefore, it promotes cancer cell proliferation." (PMID 31579438, 2019).
parathyroid hyperplasia (1 paper, 2025). A hyperplasia that involves the parathyroid gland. "In adolescents, mutations in MENIN (MEN1), RET (MEN2), CDKN1B (MEN4), and CDC73 (HPT-JT) predominate, usually leading to multiglandular parathyroid hyperplasia in syndromic forms of PHPT." (PMID 40666157, 2025).
periodontal disease (1 paper, 2025). "The most robust associations found for each phenotype are as follows: DMFT with rs79198416 (near CDC73/KCNT2; p = 7.57E-07), periodontal disease with rs73870587 (DIPK2A, p = 7.38E-08); CIMT with rs113152669 (LRP1Bp = 4.07E-07), and CAC with rs76676138 (CNTNAP2; p = 2.47E-19)." (PMID 41006734, 2025).
renal oncocytomas (1 paper, 2021). "It is worth mentioning that CDC73 somatic mutations have been detected in a small number of sporadic renal oncocytomas in one study, which however does not appear sufficient to infer a causative role of parafibromin in oncocytic transformation per se." (PMID 34831144, 2021).
serous adenocarcinoma (1 paper, 2017). An adenocarcinoma that is characterized by the presence of papillary patterns and cellular budding. "There was a lower CDC73 expression in normal ovary than that in serous cystoadenocarcinoma, clear cell, endometriod, mucinous and serous adenocarcinomas (p<0.05)." (PMID 29221126, 2017).
somatotrophinoma (1 paper, 2020). "Thus, our report of a patient with PNEN and somatotrophinoma who had a CDC73 variant, provides further evidence that CDC73 variants may result in a MEN1 phenocopy." (PMID 33150274, 2020).
T-cell leukemia (1 paper, 2025). A malignant disease of the T-lymphocytes in the bone marrow, thymus, and/or blood. "CDC73, full named cell division cycle 73, has been demonstrated to regulate Notch-induced T-cell leukemia cells in various disorders." (PMID 41318472, 2025).
virus infection (1 paper, 2015). "With regard to virus infection, IAV-induced SUMOylation of CDC73 appears to potentiate its function in transcription elongation of genes promoting antiviral immunity." (PMID 26549460, 2015).
tumor (83 papers, 2009 to 2026). "CDC73-mutant PCs exhibit a higher tumor mutational burden, genomic instability, and metastatic potential." (PMID 40362680, 2025). "Nonetheless, one of the most thoroughly examined genes in this context is CDC73 (formerly HRPT2), which encodes parafibromin, a tumor-suppressor protein that plays a critical role in transcriptional regulation, cell proliferation, and tumor suppression." (PMID 40806850, 2025). "Inactivated mutation of the CDC73 gene results in loss of parafibromin staining in the nuclei of tumor cells." (PMID 38340242, 2024). "FAT1, which like CDC73 functions as a tumour suppressor, was found associated with CDC73 in independent AP-MS experiments in 293T and MDA-MB-231 cells and we thus focused on this interaction for this study." (PMID 34424918, 2021). "Tumour-derived inactivating mutations in both Merlin and the CDC73 PAFC subunit mutually disrupt their interaction and growth suppression by Merlin requires CDC73." (PMID 34424918, 2021). "CDC73 is a tumour suppressor gene encoding the parafibromin protein, a transcriptional and post-transcriptional regulator targeting both the Wnt/beta-catenin and Hedgehog pathways." (PMID 31838586, 2020). "This syndrome is caused by the CDC73 inactivation mutation on the chromosome 1q25 responsible for protein excretion by a tumor suppression function, called parafibromin." (PMID 30317121, 2018). "Development of HPT-JT associated tumours was assessed in 69 mice (21 Cdc73+/+ mice (9 males and 12 females) and 48 Cdc73+/− conventional knockout mice (12 males and 36 females)) between the ages of >7 to <24 months." (PMID 28288139, 2017). "Among many known HRR proteins, the top hit of our validation experiments was CDC73, which is encoded by the HRPT2 tumor suppressor gene." (PMID 27462432, 2015). "The aim of this study was to characterize a novel somatic CDC73 missense mutation (Ile60Asn) identified in the mandibular tumor of a HPT-JT patient carrying a germline CDC73 inactivating mutation." (PMID 24842573, 2014). "CDC73 gene inactivating mutations are also associated with other neoplasia such as clear cell, papillary, chromophobe renal cell carcinomas, oncocytomas, Wilms tumour and more rarely biliary duct carcinoma." (PMID 24340015, 2013). "Genomic profiling revealed a CDC73 mutation and high tumor mutation burden." (PMID 42137300, 2026). "CDC73 was initially found to be widely mutated in Primary Hyperparathyroidism-Jaw Tumor Syndrome, and according to following studies, a significant correlation was discovered between CDC73 and tumor metastasis /invasion in the sporadic parathyroid carcinoma." (PMID 40038693, 2025). "The tumor suppressive activity of FoxA2 is associated with its induction of Dkk1, Cu12 and Cdc73." (PMID 37298091, 2023). "The tumor mutation burden was low (1.7 m/Mb) except in three cases with CDC73 mutations > 20 m/Mb." (PMID 35326576, 2022). "Two somatic nonsense mutations (c.Glu474X and p.Glu537X), presumably inactivating both the two gene alleles, were found in a PC sample bearing a concomitant CDC73 mutation, suggesting a possible synergic effect of these two mutated tumor suppressor genes in determining malignant cancer development." (PMID 35282432, 2022). "We next considered whether tumour derived inactivating mutations in CDC73 might exhibit deficiencies in its interaction with Merlin in co-transfection experiments." (PMID 34424918, 2021). "Furthermore, tumour derived inactivating CDC73 mutations disrupt its interaction with Merlin whereas conversely, inactivating Merlin mutations disrupt the interactions with the PAFC." (PMID 34424918, 2021). "CDC73 is a tumour suppressor gene that encodes parafibromin." (PMID 31176307, 2019).
tumor (continued). "This study demonstrated, in an ossifying fibroma of the jaw arising in a HPT-JT patient, the presence of a somatic CDC73 mutation that probably represented the “second hit” in tumor development, since it led to decreased parafibromin expression and loss of its nucleolar localization." (PMID 24842573, 2014). "As of this, tumor material with CDC73 mutations is hard to obtain." (PMID 23029479, 2012). "Therefore, en bloc surgery may be more beneficial for PC patients with CDC73 abnormalities, a tumor tissue Ki67 index ≥ 5%, and high-risk Schulte staging." (PMID 36010997, 2022). "Only a limited portion of tumor tissue is used for CDC73 sequencing, whereas more tissue can be observed in IHC." (PMID 40881643, 2025). "Given the rarity of double somatic mutations in the CDC73 gene, we performed WES on his tumor tissue for confirmation." (PMID 40434298, 2025). "Somatic inactivation of CDC73 in tumor DNA is common in sporadic PC, occurring in up to 75% of cases." (PMID 36900197, 2023). "Notably, all four samples with CDC73 two-hit mutations (P5, P6, P11, and P22) showed elevated intratumor variant allele frequency (VAFtumor) of somatic variants, while the VAFtumor of germline variants decreased in tumor DNA, suggesting copy number gains in CDC73Som and/or losses in CDC73Germ." (PMID 37121965, 2023). "In this study, we present for the first time that CDC73 is the critical molecule for countering UBR5’s pivotal activities not only on TNBC tumor growth, but also on metastasis, the current major clinical problem in human cancer." (PMID 35551175, 2022). "Knocking down CDC73 expression had little effects on cell proliferation and apoptosis of these cells in vitro, whereas it almost completely restored tumor growth of 4T1/Ubr5−/− cells in mice." (PMID 35551175, 2022). "Collectively, these results suggest that the tumor suppressor CDC73 is a key regulatory protein that can block UBR5’s activities on tumor growth and lymphocyte mobilization." (PMID 35551175, 2022). "CDC73 was initially proposed to be a tumor suppressor that repressed the expression of cyclin D1 and the c-myc proto-oncogene." (PMID 35742816, 2022). "The CDC73 subunit of the PAFC functions as a tumour suppressor and we show CDC73 is required for growth inhibition by Merlin." (PMID 34424918, 2021). "Transcripts coding for tumor-suppressing proteins (Apc, Brca2, and Cdc73) are upregulated while tumor-promoting protein transcripts are downregulated (Met, Junb, and Pim1)." (PMID 32970688, 2020). "Meanwhile, we also measured the expression of miR-182-5p and CDC73 expression in tumor tissues and found that in the circ_0000140 overexpression group, miR-182-5p expression was remarkably inhibited and the CDC73 protein level was significantly increased." (PMID 32863766, 2020). "Mice were aged to 18-21 months and studied for survival, tumour development and proliferation, and serum biochemistry, and compared to age-matched wild-type (Cdc73+/+ and Cdc73+/+/PTH-Cre) littermates." (PMID 28288139, 2017). "This increased frequency of somatic CDC73 mutations is similar to that occurring for the neurofibromin 1 (NF1) gene, another tumor suppressor, in which somatic non‐synonymous mutations were ∼80‐fold more frequent than germline mutations." (PMID 28881068, 2017). "Another OSCC tumor promoter is miR-155, which targets tumor suppressor gene Cdc73 (cell division cycle 73) and, via this mechanism, increases cell proliferation and reduces apoptosis." (PMID 29206174, 2017). "Both tumor-suppressing and oncogenic effects of CDC73 rely on the N-terminal portion of hCDC7318,20." (PMID 29142233, 2017). "As Cdc73 or Parafibromin belongs to the PAF complex, it would be interesting to analyze the contribution of Cdc73 in tumor progression." (PMID 26689992, 2016). "This adds CDC73 to the long list of DSB repair tumor suppressor genes preventing cancer by promoting genome stability." (PMID 27462432, 2015).
tumor (continued). "Our study presents a new mechanism of action of CDC73, which provides important new insights into the tumor suppressor role of CDC73 in cancer." (PMID 27462432, 2015). "PCR products using Genomic DNA extracted from tumor tissues or blood as template was sequenced for HRPT2/CDC73 gene." (PMID 23029104, 2012). "Moreover, further exploration of molecular profiling is mandatory, in addition to understanding the role of epigenetic mechanisms (such as histones modification and DNA methylation) interplaying with CDC73-related tumours." (PMID 38396977, 2024). "Moreover, we present evidence that CDC73 modulates UBR5’s tumorigenic properties by tumor cell-intrinsic mechanisms as well as those that affect the tumor microenvironment (TME)." (PMID 35551175, 2022). "Hence, CDC73 functions like a tumor suppressor in TNBC as most previous studies showed, instead of an oncogene as some reports suggested." (PMID 35551175, 2022). "Both the tumor-suppressive and oncogenic effects of CDC73 rely on the N-terminal portion of CDC73." (PMID 35742816, 2022). "Thus, inactivating mutations in CDC73 disrupt the interaction with Merlin without necessarily influencing the interaction with other PAFC subunits, suggesting that the ability to interact with Merlin is important for CDC73 tumour suppressor function." (PMID 34424918, 2021). "Furthermore, 19 CDC73 alterations were observed in 18 (53%) PC samples —including four samples exhibiting tumor invasion into the adjacent tissue and three lesions—followed by alterations in EZH2 (n = 2, 6%) and HIC1 (n = 2, 6%)." (PMID 33778063, 2021). "However, little is known about how CDC73 and CTR9 function as tumor suppressors, particularly since mutations in the genes encoding the other members of the Paf1 complex have not yet been linked to the development of cancer." (PMID 29320491, 2018). "These analyses enhance our understanding of how Cdc73, as a subunit of the Paf1 complex, suppresses genome instability, and provide insights into how its human homolog may function as a tumor suppressor." (PMID 29320491, 2018). "Here we have investigated how the Paf1 complex acts to suppress genome instability with the goal of shedding light on how the human homolog of CDC73 may function as a tumor suppressor." (PMID 29320491, 2018). "The tumor showed loss of parafibromin expression; germline testing revealed no pathogenic germline variants of CDC73, suggesting either a cryptic germline variant or a sporadic malignancy." (PMID 30455668, 2018). "The restoration of Cdc73 expression by miR-155 inhibition stops tumor growth in vivo." (PMID 29206174, 2017). "The development of these tumours resulted in Cdc73+/− mice having a reduced survival." (PMID 28288139, 2017). "Identification of a somatic mutation in the wild-type CDC73 allele in the tumor has been important in confirming that the “second hit” hypothesis for tumor suppressor genes applies to CDC73." (PMID 28774260, 2017). "Discrepant results were observed in six cases: loss of parafibromin and no CDC73 mutation in four tumor samples and the opposite in two." (PMID 24145611, 2013). "While the tumor showed partial parafibromin loss, the mutational status of CDC73 was not reported." (PMID 40762649, 2025). "This suggested that CDC73 might function as a tumor suppressor, consistent with previous findings." (PMID 35742816, 2022). "Interestingly, CDC73 is also a well known tumor suppressor gene." (PMID 30541148, 2019). "No CDC73 mutation or loss of parafibromin staining was observed in the remaining 14 tumor samples." (PMID 24145611, 2013). "Collectively, these findings uncover a central role of CDC73 in antagonizing UBR5’s tumorigenic activities in a cell-intrinsic manner for tumor metastasis and extrinsically for tumor growth involving the adaptive immune system." (PMID 35551175, 2022).
tumor (continued). "Cell division cycle 73 (CDC73), which is a member of the PAF1 complex, is another tumor suppressor that directly interacts with RNF20/40 and is required for maintenance of H2BK120ub levels." (PMID 35954248, 2022). "Inactivating mutations of the CDC73/HRPT2 (henceforth CDC73) gene, encoding the 531 amino acid nuclear parafibromin protein, have been found in HPT-JT patients, while biallelic inactivation of this gene may be seen in sporadic parathyroid carcinoma, consistent with a tumour suppressor function." (PMID 24340015, 2013). "The results indicated that CDC73, PSMC2, SOCS3, and ETV4 were substantially upregulated in tumor group than that in control group, whereas PLK2 and LMO7 were substantially downregulated in tumor group than that in control group." (PMID 41318472, 2025). "Therefore, changes happened in the tumor suppressor genes MEN1 and CDC73, triggering disequilibrium of H3K4 and H3K9 activities." (PMID 35628190, 2022). "Furthermore, assuming that the tumour was sporadic, neither the sequencing of CDC73 gene was carry out." (PMID 33343947, 2020). "Two tumour suppressors, CDC73 (cell division cycle 73) and Smurf2 (smad ubiquitin regulatory factor 2), have been reported to regulate this ubiquitination reaction, and this may represent a major mechanism by which mutations in these tumour suppressors exert their tumorigenic effect." (PMID 24792170, 2014).